PEX16 (peroxisomal biogenesis factor 16)
Description:
Required for peroxisome membrane biogenesis. May play a role in early stages of peroxisome assembly. Can recruit other peroxisomal proteins, such as PEX3 and PMP34, to de novo peroxisomes derived from the endoplasmic reticulum (ER). May function as receptor for PEX3.
Synonyms: PBD8A; PBD8B
Tractability: Antibody: UniProt predicts a signal peptide or a membrane-spanning region. PROTAC: ubiquitination databases record sites on it; its protein half-life has been measured.
Target class: Other cytosolic protein
Gene: Protein-coding gene on chromosome 11 (45,909,663 to 45,918,812, reverse strand). Ensembl gene ENSG00000121680.
Subcellular location: Peroxisome membrane
Pathways (Reactome):
Protein localization: Class I peroxisomal membrane protein import
Gene Ontology:
Molecular function: protein binding
Biological process: ER-dependent peroxisome localization; ER-dependent peroxisome organization; peroxisome membrane biogenesis; peroxisome organization; protein import into peroxisome matrix; protein import into peroxisome membrane; protein targeting to peroxisome; protein to membrane docking
Cellular component: endoplasmic reticulum; endoplasmic reticulum membrane; membrane; peroxisomal membrane; peroxisome; cytosol
Genetic constraint (gnomAD): Loss-of-function variants: 37 observed, 50.88 expected, observed/expected ratio (o/e) 0.73, 90% interval 0.56 to 0.96. The upper end of that interval is the gene's LOEUF score, 0.96, which puts it in group 4 of 6, group 1 being the genes least tolerant of losing a copy. Missense variants: 401 observed, 429.67 expected, observed/expected ratio (o/e) 0.93, 90% interval 0.86 to 1.01. Synonymous variants: 185 observed, 187.89 expected, observed/expected ratio (o/e) 0.98, 90% interval 0.87 to 1.11.
Gene-disease validity (ClinGen):
ClinGen rates the evidence that PEX16 causes each of these diseases.
peroxisome biogenesis disorder (autosomal recessive): Definitive.
Homologues: Orthologues: chimpanzee PEX16 (99% identical), macaque PEX16 (94% identical), pig PEX16 (94% identical), dog PEX16 (92% identical), mouse Pex16 (91% identical), rat Pex16 (91% identical), guinea pig PEX16 (90% identical), rabbit PEX16 (86% identical), zebrafish pex16 (67% identical), tropical clawed frog pex16 (56% identical), Drosophila melanogaster Pex16 (36% identical).
Diseases named in the same sentence as PEX16 in open-access papers:
PEX16 is named in the same sentence as 32 diseases in open-access papers, as found by Europe PMC text mining. Sharing a sentence is not in itself a finding about the gene and the disease. The quoted sentences say what the papers report.
Ataxia (5 papers, 2011 to 2025). Ataxia refers to impaired coordination of voluntary muscle movement. "While this work was in progress, PBD patients with mild phenotypes including cerebellar ataxia were shown to have mutations in PEX10 gene or PEX16 gene." (PMID 21392394, 2011). "Mutations in PEX16 have been shown to cause HSP complicated by cerebellar ataxia and dystonia." (PMID 33646413, 2021). "This atypical ataxia phenotype for PEX16 has been characterized by other groups but lacks the classic features of PBD-ZSD, and its relationship to the classic spectrum has been unclear." (PMID 39605732, 2024). "Severe alleles in PEX genes lead to severe clinical presentations, but in recent years, the mild presentations due to PEX mutations have expanded from phenotypes labeled as “infantile Refsum disease” to include atypical ataxia in PEX16 and Heimler syndrome in PEX1 and PEX6." (PMID 39605732, 2024).
Zellweger spectrum disorders (5 papers, 2011 to 2025). The most severe variant seen in the peroxisome biogenesis disorders that is characterized by neuronal migration defects in the brain, dysmorphic craniofacial features, profound hypotonia, neonatal seizures, and liver dysfunction. "Intriguingly, case studies of PEX16 mutations have also documented atypical Zellweger spectrum disorder phenotypes including dystonia, cerebellar ataxia, corticospinal tract degeneration, peripheral neuropathy and spasticity, with normal levels of VLCFAs." (PMID 40949164, 2025). "PEX16 is essential for peroxisome biogenesis as its absence results in the loss of peroxisomal membrane and is associated with Zellweger syndrome and leukodystrophy." (PMID 37338571, 2023). "Mutations in PEX16 can cause peroxisomal biogenesis disorder 8A (Zellweger, OMIM 614876) and 8B (OMIM 614877), for which this variant has been reported as likely pathogenic (ClinVar 209181)." (PMID 27679996, 2016). "The human peroxin genes PEX3 or PEX16 are required for peroxisomal membrane protein targeting, and their mutations cause Zellweger syndrome, a class of PBDs." (PMID 21826223, 2011). "Peroxisome contribution to cellular adaptation during ER stress was analyzed by comparing the survival of human primary fibroblasts derived from a Zellweger Spectrum Disorder patient carrying homozygous PEX16 R176* mutations (hereafter referred to as pex16KO) to WT47." (PMID 41315397, 2025). "Here, we developed potential Drosophila models for Zellweger syndrome, in which the Drosophila pex3 or pex16 gene was disrupted." (PMID 21826223, 2011). "Zellweger spectrum disorders (ZSDs), including archetypal Zellweger syndrome, neonatal adrenoleukodystrophy (NALD) and infantile Refsum disease (IRD), are PBDs caused by mutations in peroxin genes (PEX1, PEX2, PEX3, PEX5, PEX6, PEX10, PEX11β, PEX12, PEX13, PEX14, PEX16, PEX19 or PEX26)." (PMID 40949164, 2025). "We conclude that these mutants reflect broad symptoms of PBDs, and can be viewed as Drosophila models of these diseases, especially of Zellweger syndrome, although the Drosophila pex16 mutant does not recapitulate the infant death seen in Zellweger syndrome patients." (PMID 21826223, 2011).
Obesity (4 papers, 2021 to 2024). Accumulation of substantial excess body fat. "Conversely, TMEM135 overexpression promotes mitochondrial fragmentation, protects against diet-induced obesity and insulin resistance, and rescues thermogenesis in Pex16-AKO mice." (PMID 37773161, 2023). "Pex16 plays an critical role in adipose tissue peroxisomal biogenesis, and mice deficient for the Pex16 gene showed increased diet-induced obesity and impaired thermogenesis ability without skin or osteoarticular manifestations." (PMID 33816493, 2021). "Adipose-specific KO of the peroxisomal biogenesis factor Pex16 (Pex16-AKO) in mice impaired cold tolerance, decreased energy expenditure, and increased diet-induced obesity." (PMID 35326442, 2022). "After high-fat diet (HFD) feeding, body weights were increased in PEX16 floxed (Pex16fl/fl) mice and adipose-specific PEX16 knockout (Pex16AdipoQ-Cre) mice, but not in the Pex16Alb-Cre mice, suggesting that the development of obesity is regulated by liver PEX16 but not by adipose PEX16." (PMID 38790950, 2024). "To sum up, we show that hepatocyte-specific PEX16-absent mice exhibit hepatocyte proliferation, increased liver mass but decreased adipose tissue mass, alteration of fatty acids-cholesterol-bile acid metabolism, and resistance to HFD-induced hepatic steatosis and obesity." (PMID 38790950, 2024).
Hepatic steatosis (2 papers, 2023 to 2024). Steatosis is a term used to denote lipid accumulation within hepatocytes. "Together, these results show that hepatic loss of PEX16 leads to the disappearance of peroxisomes and hepatic steatosis." (PMID 37338571, 2023). "The loss of PEX16 did lead to mild hepatic steatosis, even on a control diet, despite having preserved mitochondrial function." (PMID 37338571, 2023). "Nutritional stress induced by LPD in weanlings exacerbated the hepatic steatosis caused by Pex16 deficiency." (PMID 37338571, 2023). "To better understand the etiology of hepatic steatosis caused by the loss of PEX16, we assessed relevant lipid pathways in the liver." (PMID 37338571, 2023). "Lipid staining with BODIPY further demonstrated that the Pex16 KOs fed LPD had the most severe hepatic steatosis." (PMID 37338571, 2023). "However, fenofibrate treatment reduced hepatic steatosis in Pex16 KO mice fed either a control diet or an LPD." (PMID 37338571, 2023).
peroxisomal biogenesis disorders (2 papers, 2024 to 2025). "Therefore, it is critical to study PEX genes involved in different aspects of biogenesis, such as PEX2 and PEX16, when characterizing peroxisomal biogenesis disorders." (PMID 39605732, 2024).
steatosis (2 papers, 2023 to 2024). Increased lipid within the cytoplasm of cells. "As mitochondrial function was decreased in the Pex16 KO mice fed an LPD, this is likely the most critical contributor to the exacerbated steatosis in these mice." (PMID 37338571, 2023).
axonal motor neuropathy (1 paper, 2011). "However, these patients displayed additional neurological symptoms including axonal motor neuropathy and decreased vibration sense in PEX10- mutated patients and spastic paraparesia, leukodystrophy peripheral neuropathy and cataracts in patients with PEX16 mutation." (PMID 21392394, 2011).
cyst (1 paper, 2011). A sac-like closed membranous structure that may be empty or contain fluid or amorphous material. "We overexpressed the pex16 gene specifically in cyst cells (driven by ptc-GAL4) or germline cells (driven by nos-GAL4) in the pex161 mutant background." (PMID 21826223, 2011). "When pex16 was overexpressed in cyst cells, but not germline cells, the fertility of the pex161 males was rescued (data not shown)." (PMID 21826223, 2011). "pex16 expressed in somatic cyst cells but not germline cells had an essential role in the maturation of male germline cells, suggesting that peroxisome-dependent signals in somatic cyst cells could contribute to the progression of male germ-cell maturation." (PMID 21826223, 2011). "However, early spermatocyte cysts, which are composed of 16 spermatocytes and two cyst cells, were found in these testes (data not shown), which suggests that the mitotic division of the gonialblast occurred normally in the pex16 mutant testes." (PMID 21826223, 2011).
GM1 gangliosidosis (1 paper, 2016). A rare lysosomal storage disorder characterized biochemically by deficient beta-galactosidase activity and clinically by a wide range of variable neurovisceral, ophthalmological and dysmorphic features. "We obtained a genetic diagnosis in 4/9 (44 %) families within known HSP genes (DDHD2 and CYP2U1), as well as perixosomal biogenesis disorders (PEX16) and GM1 gangliosidosis (GLB1)." (PMID 27679996, 2016).
Hyperoxaluria (1 paper, 2024). Increased excretion of oxalates in the urine. "It has been associated with hyperoxaluria with NL and NC with variants in PEX1, likely with variants in PEX5, and possibly with variants in PEX3, PEX6, PEX 10, PEX 12, PEX13, PEX14, PEX16, PEX19, and PEX26." (PMID 38606357, 2024). "It has been associated with hyperoxaluria with NL and NC with variants in PEX1 and PEX3, likely with variants in PEX5, and possibly with variants in PEX6, PEX7, PEX10, PEX11, PEX12, PEX13, PEX16, and PEX26." (PMID 38606357, 2024).
hypothyroidism (1 paper, 2021). Abnormally low levels of thyroid hormone. "Surprisingly, hypothyroidism decreased the protein expression of Pex16 on day 7 and it remained low until the end of the experiment." (PMID 34571897, 2021). "Given that depletion of endogenous Pex16 itself increased the direct incorporation of PMPs, our results indicate that hypothyroidism probably favors direct incorporation of PMPs to peroxisomes via Pex19, which hinders Pex16 expression." (PMID 34571897, 2021).
lymphoma (1 paper, 2025). A malignant (clonal) proliferation of B- lymphocytes or T- lymphocytes which involves the lymph nodes, bone marrow and/or extranodal sites. "Another investigation uncovered that the proteins PEX3, PEX16, and PEX19 safeguard lymphoma cells by counteracting cell death prompted by the histone deacetylase inhibitor." (PMID 40487257, 2025).
melanoma (1 paper, 2022). A malignant, usually aggressive tumor composed of atypical, neoplastic melanocytes. "In addition, the expression of various peroxisomal-related genes, such as DEPP and PEX16, is highly upregulated in several cancer types, including melanoma, colon, lung, ovarian, and prostate cancers, suggesting that peroxisomes are involved in tumorigenesis." (PMID 36139416, 2022).
PEX16 also shares sentences with these, for which no sentence is quoted: cerebellar ataxia (2 papers); tumor (2); Autosomal recessive spastic paraplegia type 46 (1); Breast Invasive Carcinoma (1); cancer (1); cataract (1); Dystonia (1); Insulin resistance (1); Intellectual disability (1); leukodystrophy (1); metabolic disorders (1); Niemann Pick type C disease (1); peroxisome biogenesis disorders (1); prostate carcinoma (1); Refsum disease (1); Seckel syndrome (1); spastic ataxia (1); Spasticity (1); spinocerebellar ataxia type 28 (1).